XRCC1 (X-ray repair cross complementing 1)
Diseases named in the same sentence as XRCC1 in open-access papers (continued):
Sharing a sentence is not in itself a finding about the gene and the disease.
breast carcinoma (continued). "The analysis aimed to explore the distribution of XRCC1 (rs1799782), CHEK2 (rs17879961), and XPD (rs238406) genotypes in a cohort of female breast cancer patients and their potential association with clinical characteristics and histopathological subtypes." (PMID 40507526, 2025). "Materials and Methods: This retrospective study analyzed 36 breast cancer patients from a Romanian clinic (2020–2024) with complete genetic data for XRCC1 (rs1799782), CHEK2 (rs17879961), and XPD (rs238406)." (PMID 40507526, 2025). "Base excision repair proteins including XRCC1, APE1, SMUG1, and FEN1 were significantly associated with poor breast-cancer-specific survival." (PMID 39199284, 2024). "Specifically, the phosphorylation level at the T453 locus within the XRCC1 protein was significantly elevated in breast cancer, colon cancer, LUAD, UCEC, and pancreatic adenocarcinoma compared to normal tissues (all P < 0.05)." (PMID 38217545, 2024). "Based on the data gathered, we propose, for the first time, that SOC therapies used in ER+ breast cancer reduce the expressions of DNA repair proteins, XRCC1, FEN1, BRCA1, BRCA2 and RAD51, caretakers in maintaining genomic integrity." (PMID 37914699, 2023). "Our findings indicated that the XRCC1 rs25487, XPG rs17655, XRCC3 rs861539, and hMSH2 rs4987188 were associated with breast cancer risk in the Tanzanian women." (PMID 35691022, 2023). "Previous studies have indicated that XRCC1 is involved in cisplatin resistance, and the inhibition of XRCC1 contributes to facilitating DNA single-strand breaks in breast cancer cells." (PMID 36358986, 2022). "Alterations in the XRCC1 gene and protein expression were reported following glucose concentration changes in breast cancer cell lines and hepatocytes, suggesting differences in the response between tissue and cell types." (PMID 35457130, 2022). "Berberine attenuates X-ray repair cross complementing 1 (XRCC1)-mediated base excision repair and sensitizes breast cancer cells to the chemotherapeutic drugs." (PMID 33806918, 2021). "Together, these results suggest that attenuation of XRCC1 expression influences breast cancer etiology and response to therapy." (PMID 34067421, 2021). "In breast cancer, low expression of XRCC1 correlated with improved response to poly(ADP-ribose) polymerase (PARP) inhibitors." (PMID 34067421, 2021). "Alterations of XRCC1 protein and gene expression levels are observed in many cancers, including colorectal, ovarian, and breast cancer." (PMID 34067421, 2021). "A number of studies have been conducted on XRCC1 and APE polymorphism to validate their role on gastric, breast cancer and other types of cancers." (PMID 32711433, 2020). "Further analysis of XRCC1 expression across breast cancer types shows increased expression of XRCC1 in Luminal (p < 1 x 10−12, Luminal to Normal) and TNBC (p < 0.001, TNBC to Normal) tumor types, but not in HER2 positive tumors." (PMID 31596905, 2019). "Variations in XRCC1 expression are observed in breast cancer patient samples, with low XRCC1 expression proposed as a target for PARPi treatment." (PMID 31596905, 2019). "The presented studies demonstrated that XRCC1–Gln/Gln and XPD-Gln/Gln genotypes were strongly associated with an increased risk of breast cancer." (PMID 30728902, 2019). "Genetic variations in single-nucleotide-polymorphisms XRCC1 and XRCC2 are reported to influence breast cancer susceptibility in Cypriot women aged 40–70 years." (PMID 30119676, 2018). "Both severe early gastrointestinal toxicities, nausea and vomiting, were dependent on the combination of young age of breast cancer patients and modifications in DNA repair machinery (XRCC1, p.Arg399Glu and ATM, p.Asp1853Asn)." (PMID 29507678, 2018).
breast carcinoma (continued). "A reduction in XRCC1 expression levels in human breast cancer cells resulted in decreased SSB repair capacity and hypersensitivity to DNA damage induced by methyl methanesulfonate." (PMID 29117108, 2017). "Mouse fibroblasts deficient in XRCC1 were hypersensitive to the PARP inhibitor 4-amino-1,8-naphthalimide (4-AN), and XRCC1 knockdown breast cancer cells were hypersensitive to KU0058948." (PMID 27642590, 2016). "Comparing only smoker groups, the frequencies of XRCC1, APEX1, XPD, CYP2A6*2 and CYP2A6*9 genetic polymorphisms were similar in both controls and breast cancer patients." (PMID 27754415, 2016). "Among DNA repair genes, XRCC1 Arg399Gln has been reported in breast cancer and skin cancer, while XPD C156A was correlated with basal cell carcinoma, and the hOGG1 Ser326Cys polymorphism has been studied as a causal factor in lung and esophageal cancers." (PMID 26295053, 2015). "Key base excision repair (BER) proteins, including XRCC1, APE1, SMUG1, and FEN1, were independently associated with poor breast cancer-specific survival (BCSS) (ps≤0.01)." (PMID 25111287, 2014). "Low XRCC1 (p<0.01), low APE1 (p<0.01), low SMUG1 (p<0.01), and high FEN1 (p<0.01) remain independently associated with poor breast cancer-specific survival (BCSS)." (PMID 25111287, 2014). "Nicoloso and colleagues investigated 38 previously identified breast cancer risk SNPs and found two to modify miRNA binding sites in TGFB1 and XRCC1 in vitro." (PMID 25390939, 2014). "Thus, we believed that XRCC1 Arg399Gln polymorphism maybe also associate with breast cancer." (PMID 24489692, 2014). "We therefore in this study aimed to assess the potential interactions of seven common polymorphisms from five DNA repair genes (XRCC1, XRCC2, XRCC3, XPA and APEX1) in association with breast cancer among Han Chinese women." (PMID 24642895, 2014). "Some SNPs in DNA repair related genes, such as APE1, XRCC1, ERCC1 and XPF were found to be associated with breast cancer susceptibility in Chinese Han population, so did some SNPs in cell-cycle genes such as CCNE1 and CDK2." (PMID 24386390, 2013). "In this study, we examined the role of XRCC1 Arg280His, XRCC1 Arg399Gln and XPD Lys751Gln polymorphisms in relation to breast cancer risk in a Finnish study population." (PMID 16280050, 2005). "The associations found between the XRCC1 Arg399Gln and/or XPD Lys751Gln genotypes, smoking, and breast cancer risk are biologically plausible." (PMID 16280050, 2005). "We found a statistically significant association between the XRCC1 and XPD genotypes and breast cancer risk in Finnish smoking women, especially when enzymes in both DNA repair pathways were defective." (PMID 16280050, 2005). "In this study, we evaluated the role of XRCC1 Arg280His, XRCC1 Arg399Gln, and XPD Lys751Gln polymorphisms in breast cancer susceptibility in our Finnish Caucasian study population." (PMID 16280050, 2005). "In this study, we evaluated if polymorphisms in DNA repair genes XRCC1 (Arg280His, Arg399Gln) and XPD (Lys751Gln) modify individual breast cancer risk, with emphasis on tobacco smoking." (PMID 16280050, 2005). "XRCC1 loss amplifies the sensitivity of pancreatic cancer cells to β-lapachone, triple negative breast cancers to the ATM, ATR, and Wee1 inhibitors, liver adenocarcinoma HepG2 to γ rays, and breast cancer cells to cisplatin, camptothecin, and MMS." (PMID 40271221, 2025). "Although several studies have individually explored the roles of XRCC1 (rs1799782), CHEK2 (rs17879961), and XPD (rs238406) in cancer risk, few have evaluated their combined interaction or distribution across breast cancer subtypes in a clinically annotated patient population." (PMID 40507526, 2025). "Furthermore, we observed an increased phosphorylation level at the S241 locus within XRCC1 protein in breast cancer (P = 9.4E-13), colon cancer (P = 1.7E-34), GBM (P = 4.4E-02), UCEC (P = 7.4E-20), and ovarian cancer (P = 1.1E-08)." (PMID 38217545, 2024).
breast carcinoma (continued). "Additionally, alterations in the XRCC1 gene and protein expression were reported following glucose concentration changes in breast cancer cell lines and hepatocytes." (PMID 36672885, 2023). "XRCC1 is dysregulated in multiple cancers beyond breast cancer." (PMID 35457130, 2022). "Amino acid substitution variants of XRCC1 and XRCC3 genes may contribute to breast cancer susceptibility." (PMID 35563727, 2022). "XRCC1 overexpression can inhibit breast cancer cell proliferation and metastasis." (PMID 33184404, 2020). "In protein expression, PARP1 (OR 1.147, 95% CI 1.067 ~ 1.233, P < 0.05), XRCC4 (OR 1.088, 95% CI 1.015 ~ 1.166, P < 0.05), XRCC1 (OR 1.114, 95% CI 1.021 ~ 1.215, P < 0.05), ERCC1 (OR 1.068, 95% CI 1.000 ~ 1.141, P < 0.10) were risk factors for postoperative metastasis of breast cancer." (PMID 33184404, 2020). "Defects in BER related to low XRCC1 expression may sensitize breast cancer cells to PARPi, similar to homologous recombination and BRCA1/2 defects." (PMID 31596905, 2019). "For instance, mutation R399Q was found to be positively associated to breast cancer, which is located at the end of the first BRCT domain of XRCC1 and at the interface of the best binding mode predicted by Cluspro in the ETS(Ets-1)/BRCT(XRCC1) docking run." (PMID 30857266, 2019). "Hence, the alternative polymorphic site at XRCC1 is playing a double role in breast cancer with antitumor activity and promotion of metastasis as well." (PMID 31468363, 2019). "With changes in XRCC1 expression observed in some breast cancers, we hypothesized that XRCC1 expression level changes in TNBC could indicate BER defects which could be targeted to provide new treatment strategies for this aggressive breast cancer subtype." (PMID 31596905, 2019). "Allele XRCC1-Gln (OR 6.37; 95% CI 4.86–8.35, p < .0001), hMSH2-Asp (OR 4.41; 95% CI 3.43–5.67, p < .0001), XPD -Gln (OR 2.56; 95% CI 2.02–3.25, p < .0001) and RAD51-T genes (OR 1.44; 95% CI 1.15–1.80, p = 0.002) strongly correlated with breast carcinoma." (PMID 30728902, 2019). "Pre-clinical data, albeit regarding breast cancer, has examined the synthetic lethality of inhibiting pathways for DSB in cells deficient in XRCC1 and found that potent ATM and DNA-PKc inhibitors are synthetically lethal in XRCC1 deficient cells." (PMID 29925418, 2018). "XRCC1 is a recognized tumour suppressor gene lost in breast cancer." (PMID 26781748, 2016). "The key finding was that two polymorphisms, XRCC1 gene rs25487 and XPA gene rs1800975, might exert both independent and interactive effects on the development of breast cancer." (PMID 24642895, 2014). "None of the remaining XRCC1 genotypes were significantly associated with breast cancer after including confounders." (PMID 20442803, 2010). "XRCC1 194W was associated with a non-significant increase in breast cancer, while XRCC1 280H and XRCC1 399Q were associated with a non-significant decrease in breast cancer." (PMID 20442803, 2010). "So, according to our data, these XRCC1 gene variants do not appear to have any impact on breast cancer susceptibility in the analyzed population." (PMID 21637676, 2009). "In contrast to the XRCC1 Arg399Gln polymorphisms, the Arg280His polymorphism did not significantly modify breast cancer risk in the present study." (PMID 16280050, 2005). "When subjects were studied by the stage of the disease at the time of diagnosis, a significant increase for advanced stage (III or IV) breast cancer was seen for women with the XRCC1-399 Gln/Gln genotype (OR 2.86, 95% CI 1.05–7.81) compared to those with the Arg/Arg genotype." (PMID 16280050, 2005). "No other factor examined modified the association between XRCC1 polymorphisms and breast cancer risk." (PMID 16457697, 2005).
breast carcinoma (continued). "The kinetics of XRCC1 foci in the BRCA1-deficient breast cancer cell line MDA-MB-436 are similar to those in U2OS cells and are also sensitive to niraparib treatment, suggesting that BRCA1 does not directly modulate the PAR–dependent, early recruitment of XRCC1." (PMID 32890402, 2020). "However, the frequency of XRCC1-deficiency in breast cancer is not known, and the susceptibility to PARPi across breast cancer subtypes is undefined." (PMID 31596905, 2019). "In an approach distinct from the classical case-control association studies, we compared the distribution of the most studied variants of the XRCC1 gene in women reporting FH of breast cancer with the distribution in individuals without reported breast cancer cases in the family (controls)." (PMID 21637676, 2009). "However, studies that examined the relationship between XRCC1 polymorphisms and breast cancer did not observe any meaningful differences by factors such as family history, alcohol intake, reproductive factors, ionizing radiation, and body mass index." (PMID 16457697, 2005). "Moreover, women who carried the XRCC1-399 Gln/Gln genotype and were diagnosed with early stage (I or II) breast cancer had tumours of higher grade (II or III) marginally (p = 0.065, one-sided) more often than those with the Arg/Arg genotype, 86.1% (31/36) versus 72.5 % (137/189), respectively." (PMID 16280050, 2005). "According to alcohol metabolism-involved genes, three were up-regulated (ITGA5, CBS, and SOD2), and six were down-regulated (XDH, XRCC1, MTHFR, CYP1B1, XPC, and GSTP1) among women who died for breast cancer." (PMID 39125744, 2024). "Three genes were up-regulated (i.e., ITGA5, CBS, and SOD2), while six were down-regulated (i. e, XDH, XRCC1, MTHFR, CYP1B1, XPC, and GSTP1) among individuals who died of breast cancer." (PMID 32078659, 2020). "FOXM1 regulates XRCC1 and BRCA2 in HER positive breast cancer, in triple-negative breast cancer, however, FOXM1 transactivates EXO1 and PLK4 in response to doxorubicin." (PMID 24824601, 2014). "Our analysis demonstrated significantly higher protein expression levels of XRCC1 in primary tissues of GBM, hepatocellular carcinoma, head and neck squamous carcinoma, breast cancer, colon cancer, lung adenocarcinoma (LUAD), and ovarian cancer compared to normal tissues." (PMID 38217545, 2024). "When we examined XRCC1 expression more closely in breast cancer using the UALCAN TCGA portal, we noted significantly increased expression of XRCC1 in luminal (566 cases, p < 10−12 compared with normal) and triple negative breast cancers (TNBC, 116 cases, p < 0.001)." (PMID 34067421, 2021). "Furthermore, the downregulation of XRCC1 expression resulted in increased sensitivity to the DNA damaging agent methyl methanesulfonate and decreased the SSB repair capacity in human breast cancer cells." (PMID 29117108, 2017).
breast carcinoma (continued). "In conclusion, our findings provide clear evidence that XRCC1 gene rs25487 and XPA gene rs1800975 might exert both independent and interactive effects on the development of breast cancer." (PMID 24642895, 2014). "Our findings provide clear evidence that XRCC1 gene rs25487 and XPA gene rs1800975 might exert both independent and interactive effects on the development of breast cancer among northern Chinese women." (PMID 24642895, 2014). "Our results do not indicate a major role for XRCC1 and XPD polymorphisms in breast cancer susceptibility, but suggest that they may modify the risk especially among smoking women." (PMID 16280050, 2005). "ER, HER2, E-Cad, Ki67, Molecular subtypes, XRCC1, XRCC4, 53BP1, ERCC1 and XPA were not independent prognostic factors of postoperative breast cancer metastasis (P > 0.05)." (PMID 33184404, 2020).